SPHK1 (sphingosine kinase 1)
Diseases named in the same sentence as SPHK1 in open-access papers (continued):
Sharing a sentence is not in itself a finding about the gene and the disease.
tumor (continued). "SPHK1 expression was significantly increased in HGSOC tumours from patients who experienced relapse (non‐responders) compared to those who did not relapse (responders) (p = 0.0026)." (PMID 40356021, 2025). "Then, we inhibited the synthesis of S1P by suppressing SPHK1 at the cellular level to explore the changes in the pro-angiogenic function of tumor cells and M2-like macrophages, as well as the direction of macrophage polarization." (PMID 40589755, 2025). "Inhibition of SphK1 activity (by siRNA or specific inhibitors) significantly reduces the metastatic phenotype of tumor cells, confirming that the SphK1/S1P/EDG1 signaling axis is a key regulatory hub for HCC metastasis." (PMID 41234914, 2025). "Combined inhibition of TLR4 and SPHK1 synergizes with TMZ to suppress tumor growth and reverse M2 macrophage polarization in vivo, highlighting the therapeutic promise of targeting the ENO1/TLR4-SPHK1 axis." (PMID 41353343, 2025). "Phosphorylation of sphingosine by sphingosine kinase (SPHK1) results in the pro-tumor S1P, thus SPHK1 is a key enzyme in the generation of pro-tumoral S1P." (PMID 40507361, 2025). "Previous studies have largely focused on tumor cell-intrinsic effects, such as targeting SPHK1 to inhibit S1P synthesis or enhancing SGPL1 to degrade S1P, with the aim of suppressing tumor proliferation." (PMID 40589755, 2025). "SPHK1 exhibits distinct expression patterns across various tumor types, and in most cases, its abnormal overexpression is associated with poor prognosis." (PMID 40589755, 2025). "Recent work aimed at characterizing SPHK1 JAK2/STAT3 signaling has found that SPHK1 knockdown decreased tumor infiltration by anti-inflammatory immune cells." (PMID 40507361, 2025). "In tumor microenvironment regulation, SphK1 significantly enhances tumor angiogenesis by upregulating vascular endothelial growth factor (VEGF) expression, providing metabolic support for HCC." (PMID 41234914, 2025). "While targeting downstream SPHK1 also provided therapeutic benefit by enhancing the anti-tumor efficacy of Niraparib, Echinatin demonstrates a superior advantage due to its more favorable toxicity profile." (PMID 41304867, 2025). "Consistent with our findings, another study also found significantly elevated SPHK1 protein in omental metastases compared to matched primary HGSOC tumours." (PMID 40356021, 2025). "For example, SphK1 inhibitors have been shown to suppress tumour cell proliferation and migration while enhancing the efficacy of chemotherapy drugs." (PMID 40159631, 2025). "First, immunohistochemical staining of SPHK1 was performed on six paired samples of tissues from tumor core area and adjacent normal area in CRC patients." (PMID 40589755, 2025). "Recently, many new molecules such as SKI-178, B-5335c, and compound 51/82 were designed to specifically inhibit SphK1, but all these inhibitors need to be validated in tumor growth and metastasis models." (PMID 39940821, 2025). "Parallel mechanistic studies can correlate serum S1P and SPHK1 activity with tumor tissue and CSF to confirm biological linkage." (PMID 41294712, 2025). "The results revealed high PRDX3 expression in all PCa tumor cell clusters, whereas SPHK1 expression was much lower in both PCa and mHSPC samples, indicating a high abundance of PRDX3 in PCa cells." (PMID 40849495, 2025). "Experimental validation revealed that targeting SPHK1/S1P signaling suppresses VEGFA expression in tumor cells and M2-like macrophages, thereby reducing angiogenesis and inhibiting tumor progression." (PMID 40589755, 2025). "Our study provides novel insights into the role of SPHK1/S1P pathway in macrophages polarization and their crosstalk with tumor cells." (PMID 40589755, 2025). "The sphingolipid metabolic pathway was significantly activated in OSCC, and the role of key enzyme SPHK1 regulating OSCC tumor progression and promoting metastasis has also been elucidated." (PMID 40135589, 2025).
tumor (continued). "SphK1 promotes tumor cell proliferation, migration, and angiogenesis by activating signaling pathways such as PI3K/AKT/mTOR and MAPK/ERK." (PMID 41234914, 2025). "Immunohistochemical staining of ATF4 and SPHK1 was further studied in the micro-sections of tumor tissues." (PMID 39090107, 2024). "In line with this, our previous research has shown that Sphk1-KO results in a comparable 60% reduction in tumor size during the tumor growth phase following DEN administration." (PMID 38200582, 2024). "First, we uncovered a novel and previously unidentified association among SPHK1, MMP1, and PD-L1, all of which are crucial molecules in tumor initiation and progression, particularly in highly immunogenic HNSCC." (PMID 39629135, 2024). "Although SPHK1 exhibits a proapoptotic effect, much attention has been focused on the relationship between high expression and tumor development, and, as a consequence, on the potential pharmacological SPHK1 inhibition." (PMID 38731835, 2024). "Inhibition of SphK1 results in cell death in human BC cells, indicating that tumour SphK1/S1P signalling plays a vital role in growth/proliferation." (PMID 39660488, 2024). "In the current study, we elucidated the molecular mechanism by which SPHK1 regulates tumor PD-L1 expression via MMP1." (PMID 39629135, 2024). "This correlation was not explained by the expression of SPHK1 by macrophages since SPHK1 is mostly expressed at the protein level in the tumor cells of DLBCL." (PMID 38339325, 2024). "HULC is further reported its ability to affect the angiogenesis rate of HCC tumor tissue by up-regulating sphingosine kinase 1 (SPHK1), which ultimately promotes the continuous deterioration of HCC." (PMID 38334963, 2024). "S1P and SphK1 have been shown to be closely related to tumor metastasis and progression, and SphK1 signaling can promote tumor metastasis and resist apoptosis." (PMID 38523645, 2024). "Consistent with previous findings in mouse models, the knockdown of SPHK1/MMP1 significantly reduced tumor growth, increased intratumoral PD-L1+ cell density, and inhibited CD8+ T cell exhaustion." (PMID 39629135, 2024). "The pathologic examination of lung tissues section with the H&E stain also showed both the number as well as the size of tumor nodules in the lung were significantly decreased in both SPHK1 KO sublines compared to sgNT subline." (PMID 39284838, 2024). "An FDA-approved SPHK1 inhibitor FTY720 (Fingolimod) can effectively reduce tumor metastasis and also this regimen appeared to be biocompatible." (PMID 39284838, 2024). "The aim of this study was to evaluate the role of SPHK1 in anti-tumor immunity, reveal the novel molecular mechanism of PD-L1 regulation through MMP1, and further explore the clinical significance of the SPHK1-MMP1 axis in HNSCC immunotherapy." (PMID 39629135, 2024). "The results indicated that knocking down SPHK1/MMP1 reduced tumor growth rates in mice, whereas overexpression of SPHK1/MMP1 accelerated tumor growth." (PMID 39629135, 2024). "As a lipophilic yeast, the expression of sphingosine kinase 1 (Sphk1) was upregulated to promote tumor growth after M. globosa colonization." (PMID 39235230, 2024). "In particular, SPHK1 is prominently over-expressed by numerous cancer types, in many cases correlating with increased tumor grade and reduced patient survival." (PMID 38339325, 2024). "Conversely, silencing of SPHK1 resulted in a strongly decreased expression of the two M2 markers in microglia, compared to cells cultured with control tumor cells." (PMID 36672428, 2023). "On the other hand, HJURP activates EMT through upregulation of Sphingosine kinase 1 (SPHK1), causing upregulation of vimentin and N-cadherin and downregulation of E-cadherin to promote tumor cell migration, invasion, and metastasis in vivo." (PMID 37025176, 2023).
tumor (continued). "The expression level of SPHK1 (p = 0.007) was significantly positively correlated with the tumor proliferation signature instead of SPTLC3 (p = 0.616) using ssGSEA analysis." (PMID 37999228, 2023). "SPHK1 acts as an oncogene by promoting tumor cell proliferation, migration, invasion, and chemotherapy resistance." (PMID 36823149, 2023). "A cytoplasmic kinase, SphK1 is a lipid mediator that is critical for tumor cell growth, survival, and therapeutic resistance." (PMID 36839802, 2023). "Obesity‐related inflammation increases the expression of S1P, acts on S1PR1, promotes macrophage infiltration and tumor progression, and confirms the role of circulating S1P produced by tumor and SphK1/S1P/S1PR1 axis in inflammation and tumor metastasis." (PMID 37902101, 2023). "The upregulation of SphK1 has been correlated with advanced tumor stages, lymph node involvement, recurrence of tumor, and poor survival in HNSCC." (PMID 37927468, 2023). "As more research has been conducted, more findings have shown that SPHK1 protein levels in BC patients correlate with the grade of tumor progression and are potential indicators of tumor malignancy grading." (PMID 36860848, 2023). "In line with our previous results, the drug-mediated SPHK1 inhibition resulted in a strong reduction of Arg1 and Msr1 expression in the tumor-microglia co-culture." (PMID 36672428, 2023). "Based on these results, it became clear that the relationship between increased tumor aggressiveness and a higher anti-inflammatory phenotype of TAMs can be explained by the expression levels of the SPHK1 gene." (PMID 36672428, 2023). "When compared to their nearby non-neoplastic counterparts, all 10 SPGs were evidently expressed differently in tumor tissues (p < 0.05), with SPHK1 particularly showing the highest level of expression." (PMID 38028544, 2023). "SPHK1 is a biologically active metabolite of sphingosine that is involved in various tumor progression by enhancing cell proliferation and motility." (PMID 35140786, 2022). "For example, our lab has previously demonstrated how decreasing the levels of S1P by inhibiting sphingosine kinase-1 can be combined with anti-PD-1 therapy to produce an enhanced anti-tumor response in preclinical models." (PMID 35203357, 2022). "Targeting SPHK1 with PF-543 significantly inhibited the cell cycle and tumor growth in preclinical xenograft tumor models of NSCLC." (PMID 36361531, 2022). "Our previous study has shown that SphK1 mRNA transcript is overexpressed in tumor tissues of OSCC patients compared to adjacent normal tissues from the same patient." (PMID 35494957, 2022). "Consistent with the gene expression analysis, the present study also reports a significant elevation in the levels of SPHK1 proteins in tumor tissues as compared to adjacent normal." (PMID 36309544, 2022). "SphK1 promotes tumor progression, invasion, metastasis, and chemoresistance and is a well-established oncogene." (PMID 35494957, 2022). "In this experiment, we found that delivery of EVs collected from cells that ectopically expressed SPHK1 increased tumor weight, ascites volume, and body weight compared with EVs isolated from parental cells." (PMID 35289120, 2022). "Collectively, these data illustrate that inhibition of SPHK1 or S1PR3 triggers autophagic death in tumor tissues and slows the occurrence and development of tumors." (PMID 36543771, 2022). "Overall, these data show that SPHK1 loaded into EVs can increase S1P levels in the tumor microenvironment, further promoting immune suppression." (PMID 35289120, 2022). "Immunoblot analysis of the tumor lysates also showed that tumors with high SPHK1 expressed high levels of both SPHK1 and PD‐L1 compared to their controls." (PMID 35289120, 2022). "Overexpression of SphK1 is effective in promotion, while its inhibition reduces tumor growth, angiogenesis, and chemoresistance in various xenograft models." (PMID 36362323, 2022).
tumor (continued). "In this study, we aimed to explore the regulation of IFN-γ-induced PD-L1 expression by SPHK1 to mimic the immune microenvironment in the vicinity of tumor cells." (PMID 36050478, 2022). "The key mechanism identified in this study involved an anticancer mechanism that regulates tumor growth, VM, tumor proliferation, apoptosis, and reactive oxygen species (ROS) by inhibition of the SPHK-1/HIF-1α pathway." (PMID 36139362, 2022). "A mechanistic analysis revealed that MTA3 functions as the downstream target of SPHK1 in transcriptionally regulating tumor PD-L1." (PMID 36050478, 2022). "Studies using tumor models have also shown some reduction in angiogenesis by pharmaceutically targeting SphK1, but these studies contradict one another and are further complicated by the role that S1P plays in tumor cell growth and proliferation." (PMID 36139489, 2022). "The pooled results demonstrated that SPHK1 overexpression was significantly related to clinical stage, tumor invasion, lymph node metastasis, and distant metastasis." (PMID 35126792, 2022). "Sphk1/S1P/S1PRs axis plays an important role in injuries such as fibrosis, inflammation, tumor cell migration and invasion." (PMID 36339341, 2022). "Here, extracellular vesicles (EVs) are identified as the key transporters of SPHK1 to the tumor microenvironment." (PMID 35289120, 2022). "Western blotting data for tumor tissues showed that chrysin treatment decreased SPHK-1, HIF-1α, and PARP expression while inducing caspase-3 cleavage." (PMID 36139362, 2022). "The overexpression of SPHK1 contributes to tumor progression and development, but the role of SPHK1 in antitumor immunity is unclear." (PMID 36050478, 2022). "SphK1, a key enzyme involved in S1P synthesis, promotes tumor progression, invasion, metastasis, and chemoresistance in HNSCC, and its expression level correlates with patient survival." (PMID 35494957, 2022). "SPHK1 markedly increased tumor growth at the primary injection site and distant organs in the peritoneal cavity." (PMID 35289120, 2022). "Altogether, these findings support the notion that the inhibition of SPHK1 by PF543 suppresses tumor cell growth by decreasing PD-L1 expression and subsequently enhancing CTL activity." (PMID 36050478, 2022). "As expected, tumor weight, ascites volume, and body weight drastically increased in the mice treated with EVs containing ectopically expressed SPHK1 compared to the group treated with EVs from parental cells." (PMID 35289120, 2022). "Total tumor weight and the number of tumor nodules increased when we ectopically expressed SPHK1 compared to control." (PMID 35289120, 2022). "Our IHC also showed a marked decrease in SPHK1, PD‐L1, and Ki67 levels in tumor cells after PF543 treatment." (PMID 35289120, 2022). "We found that tumor growth was slower when mice were injected with EVs isolated from SPHK1−/− cells compared to EVs collected from WT cells." (PMID 35289120, 2022). "Overexpression of SPHK1 promoted the proliferation in several tumor types, while blockade of SPHK1 inhibited tumor growth." (PMID 35126792, 2022). "Preclinically, we found that anti-PD-1 monoclonal antibody (mAb) treatment significantly rescued tumor SPHK1 overexpression or tumor MTA3 overexpression-mediated immune evasion." (PMID 36050478, 2022). "Cytoplasmic positivity for SphK1 was observed in most tumor cases in malignant squamous epithelial cells." (PMID 35494957, 2022). "Intriguingly, we observed that SPHK1- or MTA3-induced tumor proliferation was substantially suppressed by anti-PD-1 mAb treatment, as demonstrated by a reduction in the tumor growth rate." (PMID 36050478, 2022). "We performed integrative analyses including bioinformatics analysis, functional study, and clinical validation to investigate the role of SPHK1 in tumor immunity." (PMID 36050478, 2022).
tumor (continued). "Immunohistochemistry of the tumor tissues demonstrated that the ectopically expressed SPHK1 group had increased levels of the proliferation marker Ki67 and both SPHK1 and PD‐L1." (PMID 35289120, 2022). "In our tumor collection, both SphK1 and S1P1 were expressed in long and flat bones together with GLUT-1." (PMID 35158767, 2022). "The mRNA and protein expression of SphK1 and SphK2 in pCCa-1 tumor tissues were unchanged after SKI-V treatment." (PMID 35541904, 2022). "In pathogenesis of ER-positive breast cancer, SPHK1/S1P axis and estrogen receptor signaling have been known to interact with one another, leading to enhanced tumor growth and therapy resistance." (PMID 34820423, 2021). "Most studies focused on the development of SphK1 selective inhibitors, based on the over-expression of SphK1 in inflammatory immune related-diseases and tumor pathology." (PMID 34737701, 2021). "Immunohistochemical analysis revealed high expression levels of SPHK1 in 248 (24.7%) tumor samples and low expression levels in 757 samples (75.3%)." (PMID 33660008, 2021). "Expression levels of SphK1 are significantly higher in CRC cells and tissues compared to normal colonic mucosa, and are associated with more advanced tumor stages and a poorer prognosis in CRC patients." (PMID 34768523, 2021). "On the other hand, SphK1 upregulation notably abrogated anti-tumor functions of miR-128, which promotes proliferation and metastasis and reduces apoptosis." (PMID 35201458, 2021). "Further, the direct target for miR-124 is the sphingosine kinase 1 (SPHK1) gene transcript involved in the regulation of cell proliferation, adhesion, chemotaxis, migration and tumor growth, among others." (PMID 34680611, 2021). "The inhibition of SPHK1 activity can enhance sensitivity of tumor cells to chemoradiotherapy, suggesting the superiority of combination therapy." (PMID 34766135, 2021). "They showed that the activation of the SphK1/NF-κB/FSCN1 pathway was associated with poor patient survival and distance metastasis, whereas inhibition of SphK1 or NF-κB remarkably inhibited tumor growth and lung metastasis in a TNBC mouse model." (PMID 35201458, 2021). "SphK1 is significantly expressed in the non-small cell lung cancer (NSCLC) cells corresponding to tumor growth and the poor survival rates of NSCLC patients." (PMID 33920887, 2021). "The epithelial marker CDH1 was downregulated when SPHK1 was overexpressed, some tumour-related metabolic processes, such as cell invasion and migration, were promoted, and the EMT process was induced." (PMID 34857818, 2021). "We validated five regulated alternative splicing events affected by PCBP1 using RT-qPCR and found that there was a significant difference in the expression of APOC1 and SPHK1 between tumour and normal tissues." (PMID 34857818, 2021). "Recent study demonstrated a role for SphK1/S1P in the attenuation of anti-tumor functions of T cells by inhibiting their bioenergetics." (PMID 34069611, 2021). "The switch from estrogen/ER-mediated tumorigenesis to SPHK1/S1P/EGFR-activated tumor growth has been regarded as important mechanism for acquiring endocrine resistance in ER-positive breast cancer." (PMID 34820423, 2021). "SphK1 is highly expressed in various immune cells and tumor cells, and enhances the inflammatory response by triggering pro-inflammatory signals." (PMID 34737701, 2021). "STAT1 has shown tumor-suppressing properties, and when SphK1 was decreased, STAT1 signaling increased as well, leading to cell apoptosis." (PMID 33758708, 2021). "It is worth noting that SphK1 was upregulated in BC tissues in comparison to that in corresponding non-tumor tissues by analyzing the TCGA and GTEx dataset (12.03 vs. 6.36)." (PMID 33400245, 2021). "The AUC values for CERK and SPHK1 depicted a fair and significant potential to discriminate between tumor and adjacent normal tissues in local and TCGA cohort respectively." (PMID 32170160, 2020).